VCAN (versican)
Diseases named in the same sentence as VCAN in open-access papers (continued):
Sharing a sentence is not in itself a finding about the gene and the disease.
Lymphatic Metastasis (1 paper, 2023). Transfer of a neoplasm from its primary site to lymph nodes or to distant parts of the body by way of the lymphatic system. "Further studies are needed to determine the immune microenvironment of positive lymphatic metastasis patients and whether VCAN affects the expression of immune cells." (PMID 37108649, 2023). "We found that UTUC patients with positive lymphatic metastasis often have a poor prognosis, and the degree of methylation in the VCAN intron 2 measured in chromosome methylation analysis can be a predictive factor for UTUC patients with positive lymphatic metastasis." (PMID 37108649, 2023).
macrosomia (1 paper, 2023). "The 9 indicators verified by nomogram in this analysis, including pre-pregnancy BMI, weight gain at 24 gw, parity, OGTT 2 h glucose at 24 gw, HDL and LDL at 24 gw, and plasma expression of CLUL1, VCAN and RNASE3 at 24 gw, are very meaningful in terms of identifying macrosomia risk in GDM." (PMID 36788507, 2023). "The Model included pre-pregnancy BMI, weight gain at 24 gw, parity, OGTT 2 h glucose at 24 gw, HDL and LDL at 24 gw, and plasma expression of CLUL1, VCAN and RNASE3 at 24 gw had good prediction performance for predicting macrosomia in women with GDM." (PMID 36788507, 2023).
malignant mesothelioma (1 paper, 2011). A malignant neoplasm of the pleura or peritoneum, arising from mesothelial cells. "The tyrosine kinase inhibitor genistein can block versican expression induced by growth factors in malignant mesothelioma cell lines." (PMID 22096483, 2011).
medulloblastoma (1 paper, 2021). A malignant, invasive embryonal neoplasm arising from the cerebellum. "Versican isoforms are differentially distributed in gliomas, medulloblastomas, schwannomas, neurofibromas, and meningiomas." (PMID 34409033, 2021). "Versican V0 and V1 are found in all tissues, Versican V3 is found in all tissues except medulloblastomas." (PMID 34409033, 2021).
membranous nephropathy (1 paper, 2012). "Finally, a highly significant upregulation of renal versican, i.e. 8.0 fold (p<0.001) increase over control, was observed in rats with Passive Heymann Nephritis (PHN) - a severe model of proteinuric nephropathy which partly resembles human membranous nephropathy (MN) - studied at 6 months." (PMID 23024773, 2012).
mucinous tumors (1 paper, 2013). "Stromal versican expression was more often present in the central area of the tumor in stage III patients than in stage II patients (P = 0.04), and mucinous tumors had less versican expression in the stroma of the periphery of the tumor (P = 0.002)." (PMID 22711178, 2013).
myeloid leukemia (1 paper, 2019). A clonal proliferation of myeloid cells and their precursors in the bone marrow, peripheral blood, and spleen. "Next, we examined VCAN mRNA and protein levels in three human myeloid leukemia cell lines." (PMID 31777586, 2019).
Nephropathy (1 paper, 2012). A nonspecific term referring to disease or damage of the kidneys. "Results in humans were reproduced in three animal models of nephropathies in which renal versican expression was significantly increased in diseased animals as compared to controls." (PMID 23024773, 2012). "In ADR and in PHN nephropathy versican expression was also increased on the protein level." (PMID 23024773, 2012).
neuroblastoma (1 paper, 2017). Neuroblastoma (NB) is the most common solid, extracranial childhood tumor. "Y79 retinoblastoma cells and CD44-negative SK-N-DZ neuroblastoma cells transduced with adenoviral vectors in the presence of versican respond with an activation of transgene expression." (PMID 28684419, 2017).
odontogenic cyst (1 paper, 2021). A cyst in the jaw that arises from tissues of tooth development. "Therefore, versican expression may be associated to some extent with the development of odontogenic cysts, which originate from embryonic tissues of the dental organ." (PMID 33676487, 2021).
odontogenic tumors (1 paper, 2022). "While other findings observed that there was a positive versican expression in the stroma of odontogenic tumors." (PMID 36338393, 2022).
Oligomenorrhea (1 paper, 2017). Infrequent menses (less than 6 per year or more than 35 days between cycles). "We used multiple linear regression analysis with stepwise method to evaluate the predictive effects of independent variables [like serum versican level, HOMA-IR index, Ferriman-Gallwey score (FGS) higher than 8, oligomenorrhea] on PCOS which is a dependent variable." (PMID 27908842, 2017).
oral cancer (1 paper, 2018). "In this regard it is of interest that, TLR2/6 is also activated by a host matrix protein versican, the expression of which predicts progression and poor prognosis in oral cancer." (PMID 29467931, 2018).
Osteopenia (1 paper, 2018). Osteopenia is a term to define bone density that is not normal but also not as low as osteoporosis. "The upregulated proteins from SDEs of osteopenia, such as amyloid precursor protein (APP), NCL, and VCAN, interact with proteins implicated in cellular adhesion and formation of osteoclasts." (PMID 29603567, 2018). "Our analysis indicates that versican core protein (VCAN) and connective tissue growth factor (CTGF) are upregulated in SDEs of osteopenia patients and act as hubs in regulating the function of osteoblasts." (PMID 29603567, 2018).
osteosclerosis (1 paper, 2023). Abnormally high bone density. "In present study, we identified VCAN as a core hub gene of BMLs, and it was significantly associated with MSC and heterotopic-chondrocyte at single-cell level, suggesting that VCAN might be involved in aberrant ECM and osteosclerosis of BMLs." (PMID 37626330, 2023).
pancreatitis (1 paper, 2025). Inflammation of the pancreas. "In our study, plasma versican levels increased in patients with septic shock on day 1, compared to both controls and pancreatitis." (PMID 40885913, 2025).
peritoneal cancer (1 paper, 2016). A peritoneum cancer that is located in the inside of the abdomen. "In multivariate analysis, simplified peritoneal cancer index (p = 0.001), VEGF expression levels (p = 0.012), age (p = 0.030), epithelial VCAN expression levels (p = 0.042) and lymph node status (p = 0.053) were associated with OS." (PMID 26873137, 2016). "In peritoneal cancer patients, sensitivity of tumour cells to heated MMC might -at least in part- account for good outcome in patients with high epithelial VCAN expression." (PMID 26873137, 2016).
preeclampsia (1 paper, 2024). Preeclampsia is a hypertensive disorder of pregnancy that is characterized by new-onset hypertension with proteinuria presenting after 20 weeks of gestation, and depending on mild or severe forms may initially present with severe headache, visual disturbances, and hyperreflexia. "Moreover, the upregulations of angiogenesis pathway in both two subsets and coagulation pathway in VCAN+ Mono were observed in PE, these pathways were known to be of great importance to the occurrence and development of preeclampsia." (PMID 38182876, 2024). "Notably, we identified key monocyte subsets in preeclampsia, with significantly increased expression of angiogenesis pathways and pro-inflammatory S100 family genes in VCAN+ monocytes and IFN+ non-classical monocytes." (PMID 38182876, 2024). "Collectively, we uncovered monocyte subsets of VCAN+ Mono and IFN+ Non-classical Mono contributed to the inflammatory responses in PE and may be vital to the pathological process of preeclampsia." (PMID 38182876, 2024).
progeria (1 paper, 2012). "However, m-SKPs derived from patients with progeria, a disease where accelerated ageing is observed expressed less nestin and versican, suggesting that progeria m-SKPs, assayed at the same time-point as normal m-SKPs had not developed to the same degree." (PMID 23226372, 2012).
proliferative diabetic retinopathy (1 paper, 2022). Advanced retinopathy due to diabetes mellitus characterized by the formation of new vessels in the retina. "We analyzed the expression of ADAMTS proteinases ADAMTS-1, -2, -4, -5 and -13; their activating enzyme MMP-15; and the degradation products of proteoglycan substrates versican and biglycan in an ocular microenvironment of proliferative diabetic retinopathy (PDR) patients." (PMID 36144730, 2022).
proliferative glomerulonephritis (1 paper, 2012). A constellation of renal disorders characterized by an increase number of cells in the glomerulus; these disorders generally present with nephrotic syndrome, and generally progress to end stage renal failure over a matter of weeks to years, depending on the etiology. "Versican was upregulated 3.5 fold (p = 0.02) in mice with accelerated nephrotoxic serum nephritis, a model of proliferative glomerulonephritis, after 14 days." (PMID 23024773, 2012).
prostate adenocarcinoma (1 paper, 2022). "Moreover, for three of these proteins, NPM1NPM1, VCAN, and UQCRH, we were able to validate their relative increase in BCR+ compared to BCR- using prostate adenocarcinoma mRNA data in TCGA." (PMID 35954429, 2022).
pseudoglioma (1 paper, 2013). "Collagen, type II, alpha 1, versican (VCAN), frizzled family receptor 4, low density lipoprotein receptor-related protein 5, tetraspanin 12, and Norrie disease (pseudoglioma) genes were screened with direct sequencing." (PMID 24174867, 2013).
psychosis (1 paper, 2025). "VCAN codes for a constituent of perineuronal nets, which have been implicated in a range of conditions, from synaptic plasticity to drug dependency to psychosis." (PMID 40019676, 2025).
pulpitis (1 paper, 2012). Inflammation of the dental pulp. "Immunofluorescence staining demonstrated that HA co-localized with SHAP and versican underneath the amputated site in pulpitis tissues treated with MMP-3 plus NNGH, NNGH alone or saline." (PMID 23285075, 2012). "In the present study, immunofluorescence staining demonstrated that HA co-localized with SHAP and versican underneath the amputated site in pulpitis tissues treated with MMP-3 plus NNGH, NNGH alone or saline." (PMID 23285075, 2012). "However, in the same region in MMP-3-treated pulpitis tissues, HA did not co-localize with SHAP or versican." (PMID 23285075, 2012).
renal adenocarcinoma (1 paper, 2017). "VCAN is secreted into the culture media by ACHN renal adenocarcinoma cells." (PMID 28684419, 2017).
renal failure (1 paper, 2012). "Therefore, we cannot rule out the possibility that the predictive characteristics of versican V0 and V1 expression values on progression of renal failure are not – at least in part – due to increased damage of kidney tissue and poor kidney function already at time of biopsy." (PMID 23024773, 2012).
seminoma (1 paper, 2024). A radiosensitive malignant germ cell tumor found in the testis (especially undescended), and extragonadal sites (anterior mediastinum and pineal gland). "For example, the accumulation of versican in NSGCTs exhibits a stronger correlation with disease aggressiveness compared to seminomas." (PMID 38796656, 2024).
serous ovarian tumors (1 paper, 2024). "Consistent with our findings, upregulation of VCAN was observed in stromal and epithelial compartments of high-grade serous ovarian tumors and TGF-β-treated normal ovarian fibroblasts." (PMID 38962317, 2024).
skin cancer (1 paper, 2025). "When VCAN was knocked down, the skin cancer cell line A431 was weakened in terms of proliferation, migration and invasion." (PMID 40386063, 2025). "This is consistent with our finding that VCAN knockdown promotes apoptosis and reduces drug resistance in skin cancer cells." (PMID 40386063, 2025). "In addition, versican (VCAN) may be involved in the polarization of M1 macrophages in skin cancer." (PMID 40386063, 2025).
small vessel stroke (1 paper, 2018). "In the present study, the lead SNPs in chr5q14 were inversely associated with small vessel stroke, and, therefore, our study does not provide support for any vascular-mediated mechanism underlying the association of VCAN with FA and MD." (PMID 29752348, 2018).
thrombosis (1 paper, 2025). "In the current study, COL5A1, VCAN, PTGS2, ITGAV and ITGA8 were five hub genes revealed to be closed associated with thrombosis-prone plaques." (PMID 41415585, 2025). "Among them, COL5A1, VCAN, PTGS2, and ITGAV showed extremely significant increases (P < 0.01); ITGA8 was significantly decreased in the plaque group and thrombosis group (P < 0.01)." (PMID 41415585, 2025).
thymoma (1 paper, 2020). A neoplasm arising from the epithelial cells of the thymus. "Further comparison of protein expression profiles between thymoma and TSCC identified several extracellular matrix (ECM) proteins, such as CFD, TIMP1, and VCAN, that are overexpressed in TSCC and involved in complement activation and inflammation process." (PMID 31967407, 2020). "Based on the same PRM validation sample batch we also examined TSCC/thymoma marker candidates such as CNOT2/9, SHMT1, VCAN, HTRA1, and TIMP1 in parallel with CK19 in the PRM analysis (for raw fragment abundances of all PRM samples)." (PMID 31967407, 2020). "Further comparison of type B3 and TSCC proteome revealed a number of differential proteins with similar expression patterns: CNOT2/9 and SHMT1 were found with high abundance in type B3 thymoma, while the abundance of HTRA1, TIMP1, and VCAN was higher in TSCC than in type B3 thymoma." (PMID 31967407, 2020).
tooth disorder (1 paper, 2018). A disease involving the calcareous tooth. "Although VCAN mutations were never described in humans causing tooth disorders, VCAN is known to have a role in dentinogenesis and cementogenesis in animals." (PMID 30740127, 2018).
ulcerative colitis (1 paper, 2026). An inflammatory bowel disease involving the mucosal surface of the large intestine and rectum.
Umbilical hernia (1 paper, 2018). Protrusion of abdominal contents through a defect in the abdominal wall musculature around the umbilicus. "None of the polymorphisms detected in the four candidate genes outside the QTL-region on SSC14 (VCAN, MMP13, PYCR1 and VIM) obtained significant associations with umbilical hernia." (PMID 29843603, 2018). "The VCAN is shown to display high adhesive ability to endothelial cells and facilitated tube-like structure formation, and is previously suggested as a candidate to be involved in development of umbilical hernia." (PMID 29843603, 2018).
urothelial carcinoma (1 paper, 2023). A malignant neoplasm derived from the transitional epithelium of the urinary tract (urinary bladder, ureter, urethra, or renal pelvis). "However, the specific function of VCAN in urothelial carcinoma cells remains unclear." (PMID 37108649, 2023).
uterine corpus endometrial carcinoma (1 paper, 2023). A endometrial carcinoma (disease) that involves the body of uterus. "In addition, KRAS, IKBKB, and VCAN alteration frequencies across 32 human cancer types are tightly correlated, and were highest in LUAD, COAD/READ, and uterine corpus endometrial carcinoma (UCEC), cancers that commonly cause MPE." (PMID 36980752, 2023).
Uterine leiomyoma (1 paper, 2025). The presence of a leiomyoma of the uterus. "Uterine leiomyomas represent a typical fibrotic disease characterized by the upregulation of extracellular matrix (ECM) proteins, particularly collagen 1A1, fibronectin, and versican." (PMID 39860526, 2025).
uveitis (1 paper, 2013). An inflammatory process affecting a part of or the entire uvea. "Beyond the structural role in the retinal-vitreous architecture, versican is also emerging as a pivotal mediator of the inflammatory response, supporting uveitis predisposition as a clinical manifestation of WS." (PMID 24174867, 2013). "Although it has been shown that splicing mutations cause tissue-specific versican isoform imbalance, the mechanisms explaining either uveitis or the exclusively ocular phenotype are poorly understood." (PMID 24174867, 2013).